GDNF-AS1 (GDNF antisense RNA 1)
Synonyms: GDNFOS; LINC02107; LINC02119; LINC02110
Gene: Long non-coding RNA gene on chromosome 5 (37,811,589 to 38,184,717, forward strand). Ensembl gene ENSG00000248587.
Diseases named in the same sentence as GDNF-AS1 in open-access papers:
GDNF-AS1 is named in the same sentence as 1 disease in open-access papers, as found by Europe PMC text mining. Sharing a sentence is not in itself a finding about the gene and the disease. The quoted sentences say what the papers report.
infarction (1 paper, 2020). A localised pathological necrosis of tissue resulting from obstruction of the blood supply usually by a thrombus, an embolus, or vascular torsion. "Several lncRNAs with a GC-AG intron were described to play a role in neuron development and growth like the MEG3 gene, the NEAT1 gene, the SOX2-OT gene, the GDNF-AS1 (GDNF antisense RNA 1) gene and the MIAT (myocardial infarction associated transcript)." (PMID 32499820, 2020).